MACROH2A1 (macroH2A.1 histone)
Diseases named in the same sentence as MACROH2A1 in open-access papers (continued):
Sharing a sentence is not in itself a finding about the gene and the disease.
bladder cancer (5 papers, 2016 to 2020). "Loss of macroH2A1 leads to the acquisition of stem-like features and gene expression programs, which include LIN28A transcription in bladder cancer and increased NF-Kb signalling in hepatocellular carcinoma." (PMID 29495465, 2018). "By knocking down macroH2A1 expression via shRNAs in LD611 bladder cancer cells, these cells exhibited enhanced migration, invasion and self-renewal capacity, although this study did not investigate the isoform-specific function." (PMID 29339820, 2018). "Our results suggest that Lin28B/let-7 pathway is tightly regulated by macroH2A1 and its cofactors, and have a pivotal role in the bladder tumor progression and the regulation of stem-like characteristics of bladder cancer cells." (PMID 26028027, 2016). "We found that macroH2A1 is required for the suppression of Lin28B identified as a novel downstream target of macroH2A1 in bladder cancer." (PMID 26028027, 2016). "The knockdown of macroH2A1 in bladder cancer cells increased tumorigenicity, radioresistance, degeneration of reactive oxygen species, increased sphere formation capability and an increase in the proportion of side populations." (PMID 26028027, 2016). "Additionally, the expression levels of QKI and macroH2A1.1 were decreased in bladder cancer tissues." (PMID 32194406, 2020). "Here, we show that macroH2A1 knockdown promotes stem-like properties of bladder cancer cells." (PMID 26028027, 2016). "However, the regulatory roles of macroH2A1 on bladder cancer progression have not been fully elucidated." (PMID 26028027, 2016).
prostate carcinoma (5 papers, 2019 to 2024). A carcinoma that arises from epithelial cells of the prostate gland. "In prostate cancer, the expression of macroH2A1.1 and the pre-mRNA splicing regulator QKI is decreased, which indirectly proves their regulatory relationship." (PMID 39199381, 2024). "MacroH2A1.2 is a tumor suppressor and inhibits osteoclast formation in prostate cancers." (PMID 39199381, 2024). "Furthermore, macroH2A1.2 can also inhibit prostate cancer induced osteoclastogenesis via direct interactions with HP1α and H1.2, turn out inactivating a major stimulator of osteoclastogenesis, Lymphotoxin Beta (LTβ) gene in prostate cancer cells." (PMID 38542118, 2024). "MacroH2A1.1 plays an anticancer role in prostate cancer and reduces tumour malignancy." (PMID 33858382, 2021). "In addition, a tumor suppressive role of MacroH2A1, particularly of the MacroH2A1.1 isoform, has also been supposed for human prostatic cancer." (PMID 32974186, 2020).
triple-negative breast carcinoma (5 papers, 2014 to 2024). An invasive breast carcinoma which is negative for expression of estrogen receptor (ER), progesterone receptor (PR), and human epidermal growth factor receptor 2 (HER2). "However, sometimes MacroH2A1.1 also shows the opposite effect, and in one study, high expression of MacroH2A1.1 was associated with poor prognosis in triple-negative breast cancer." (PMID 33858382, 2021). "Interestingly, it was suggested that MacroH2A1 isoforms may have different effects, since reduced MacroH2A1.1 expression has been associated with a more aggressive phenotype, whereas increased MacroH2A1.1 correlated with poor prognosis in triple-negative breast cancer patients." (PMID 31164793, 2019).
Hepatic steatosis (4 papers, 2010 to 2024). Steatosis is a term used to denote lipid accumulation within hepatocytes. "However, we found that macroH2A1-deficient females exhibit liver lipid homeostasis defects that lead to hepatic steatosis." (PMID 20359320, 2010). "MacroH2A1 knock out (KO) mice display hepatic steatosis and derangements in glucose and lipid metabolism and, interestingly, when wild type mice are fed a methyl-deficient diet, which induce a fatty liver and inflammation, a total increase in the hepatic content of macroH2A1 is observed." (PMID 23372727, 2013). "We used this well established genetic model to study the expression of macroH2A1 isoforms in hepatic steatosis and HCC." (PMID 23372727, 2013). "Thus, we propose that elevated levels of TBG, the main T4 hormone carrier, could be the cause of the alteration in lipid metabolism responsible for hepatic steatosis in the absence of macroH2A1." (PMID 20359320, 2010). "We therefore exclude a relationship between hepatic steatosis and MLV overexpression in the absence of macroH2A1." (PMID 20359320, 2010).
liver cancer (4 papers, 2020 to 2024). An epithelial or non-epithelial malignant neoplasm that arises from the liver. "Our group already showed that loss of macroH2A1 leads to increased stemness and decreased proliferation in liver cancer cells." (PMID 32401230, 2020). "We took advantage of an in vitro model of liver cancer represented by HepG2 (human hepatocarcinoma) cells stably knocked down for macroH2A1 and conducted whole transcriptome profiling and deep phenotyping analysis." (PMID 34440260, 2021). "On this premise, a candidate tumor suppressor role for PER1 in liver cancer should be carefully evaluated in the context of a lack of macroH2A1 histones, but at the same time could represent a potential molecular target with implications for therapeutic strategies." (PMID 34440260, 2021).
lymphoma (4 papers, 2008 to 2024). A malignant (clonal) proliferation of B- lymphocytes or T- lymphocytes which involves the lymph nodes, bone marrow and/or extranodal sites. "Transcriptional profiling in murine tumor models and human lymphomas revealed a strong correlation between MACROH2A1 and the ability of MYC to induce tumorigenesis." (PMID 34203934, 2021).
Obesity (4 papers, 2016 to 2025). Accumulation of substantial excess body fat. "For example, deficiency of the histone variant macroH2A1.1, encoded by the H2afy gene located on mouse chromosome 13, results in greater obesity susceptibility and gut dysbiosis in females compared to males." (PMID 40862085, 2025). "Here, we have shown for the first time that genetic ablation of large histone variant isoform macroH2A1.1 exacerbated obesity and dysmetabolism induced by a HFD specifically in female, but not in male, mice." (PMID 37926763, 2023). "Here, we used a mouse model genetically depleted of macroH2A1.1 to investigate its potential epigenetic role in sex dimorphic obesity, metabolic disturbances and gut dysbiosis." (PMID 37926763, 2023). "In in vitro models of non alcoholic fatty liver disease (NAFLD), the hepatic manifestation of obesity, overexpression of macroH2A1.1 led to a reduced lipid accumulation, while macroH2A1.2 overexpression yielded opposite effects." (PMID 37926763, 2023). "In contrast, our analysis of the in vivo role of macroH2A1 in response to nutritional excess led us to discover that genetic eviction of macroH2A1 confers protection against high fat diet-induced obesity and metabolic derangements in mice." (PMID 29206173, 2017). "Generation of macroH2A1.1 transgenic murine models will prove its mechanistic role and tissue-specific interaction with macroH2A1.2 during the development of obesity in vivo." (PMID 27800025, 2016). "In KO mice generated in the pure C57BL/6 J background, modest developmental changes in macroH2A1-mediated gene regulation under a standard diet, and a very mild systemic protection against obesity upon a high fat regimen, were observed." (PMID 27800025, 2016). "This is the first study showing that macroH2A1.2 isoform strongly protects against HF-induced obesity." (PMID 27800025, 2016). "Obesity-related macroH2A1.1 dependent phenotypes using other common HFD remain to be studied." (PMID 37926763, 2023). "To investigate the potential epigenetic role specifically of macroH2A1.1 isoform in sex dimorphic obesity and metabolic disturbances, we challenged wild type (Fl/Fl) or macroH2A1.1 knockout (KO) male and female animals with a long-term high fat dietary regimen." (PMID 37926763, 2023). "It is thus evident that the expression levels of macroH2A1 isoforms are altered during obesity-related pathologies and that genetic manipulation of these proteins has a strong impact on the development of diet-induced obesity." (PMID 29206173, 2017). "The in vivo role of macroH2A1 isoforms in lipid metabolism and obesity is thus unclear." (PMID 27800025, 2016). "In our macroH2A1.1 mouse model the link between altered expression of macroH2A1 isoforms, Xi and obesity deserves to be further explored, as it might also be underlying the sexual dimorphism in gut microbiota composition and in the female bias of autoimmune diseases." (PMID 37926763, 2023).
Cirrhosis (3 papers, 2020 to 2023). A chronic disorder of the liver in which liver tissue becomes scarred and is partially replaced by regenerative nodules and fibrotic tissue resulting in loss of liver function. "Thus, protein levels of both variants of macroH2A1 (macroH2A1.1 and macroH2A1.2), an isoform of histone H2A, are increased in the livers of elderly rodents and humans and are robust immunohistochemical markers of human cirrhosis and HCC." (PMID 34633987, 2021). "Both isoforms of MACROH2A1 (MACROH2A1.2 and MACROH2A1.2) have been shown to increase with age in both rodent and human livers and are strong immunohistochemical markers of human cirrhosis and HCC." (PMID 37808522, 2023).
glioma (3 papers, 2016 to 2019). A benign or malignant brain and spinal cord tumor that arises from glial cells (astrocytes, oligodendrocytes, ependymal cells). "Our study not only advances our current knowledge of the regulation of macroH2A1 ubiquitination and stability but also reveals new functions of macroH2A1 in glioma tumorigenesis." (PMID 31488827, 2019).
Huntington disease (3 papers, 2022 to 2025). Huntington disease (HD) is a rare neurodegenerative disorder of the central nervous system characterized by unwanted choreatic movements, behavioral and psychiatric disturbances and dementia. "The macroH2A1 gene (formerly H2afy) encodes the histone variant macroH2A1, which is upregulated in Huntington’s disease and Alzheimer’s disease." (PMID 41327391, 2025).
myelodysplastic syndrome (3 papers, 2019 to 2023). A clonal hematopoietic disorder characterized by dysplasia and ineffective hematopoiesis in one or more of the hematopoietic cell lines. "The unbalanced expression of H2AFY isoforms, especially the reduction in MacroH2A1.1, will lead to the impaired differentiation of red blood cells, and will eventually lead to anaemia in myelodysplastic syndrome (MDS) patients." (PMID 33858382, 2021).
autism (2 papers, 2007 to 2024). Persistent deficits in social interaction and communication and interaction as well as a markedly restricted repertoire of activity and interest as well as repetitive patterns of behavior. "In the same covariate analyses, when considering trend-significant associations, we identified genes such as TRIM10 and GAS7, associated with schizophrenia, MACROH2A1, related to autism-like behaviors, and ADORA2A, associated with anxiety disorders." (PMID 39020437, 2024).
cutaneous melanoma (2 papers, 2020). A primary melanoma arising from atypical melanocytes in the skin. "Recent studies have examined the expression of macroH2A1 in solid tumours and its correlation with clinical pathological features, including cutaneous melanoma." (PMID 32401230, 2020). "The tumor suppression function of macroH2A1 in cutaneous melanoma was attributed to a large extent to the transcriptional suppression of CDK8, a known oncogene." (PMID 32401230, 2020). "Therefore, macroH2A1 functions as an oncogene in UM and as a tumor suppressor in cutaneous melanoma, highlighting the profound epigenetic differences between the two types of melanocyte-derived neoplasia." (PMID 32401230, 2020). "The role of macroH2A1 in cutaneous melanoma has been well studied." (PMID 32401230, 2020). "MacroH2A1 and CDK8 expression levels anti-correlate in human cutaneous melanoma patient samples." (PMID 32401230, 2020). "Contrary to cutaneous melanoma, we demonstrated immunohistochemically that macroH2A1 expression is higher in metastatic UM than in not metastatic UM." (PMID 32401230, 2020).
lung carcinoma (2 papers, 2013 to 2019). "Reduction of macroH2A1.1 protein is negatively associated with lung cancer recurrence, and later reports have shown that alternative splicing of macroH2A1 regulates cancer cell proliferation." (PMID 30806885, 2019).
non alcoholic fatty liver disease (2 papers, 2016 to 2023). "Conversely, in genetic or dietary mice models of non-alcoholic fatty liver disease (NAFLD), a disorder that is present in 90% of obese subjects, the hepatic content of macroH2A1.2, but not of macroH2A1.1, is augmented." (PMID 27800025, 2016).
viral infection (2 papers, 2022 to 2023). "Genes in clusters 1 and 2 (with decreased macroH2A1 and increased expression) were associated with response to dsRNA and inflammatory responses, as expected during viral infection." (PMID 37516914, 2023). "The enrichment of macroH2A1 and H3K27me3 was observed as large domains, many of which were gained upon viral infection, suggesting that the host landscape is altered upon infection." (PMID 37516914, 2023). "To summarize, MACROH2A1 is induced in monocytic cells in the lungs or circulating blood following COVID-19 infection, possibly in response to viral infection via the TLR signaling pathway or IFN-gamma stimulation." (PMID 36451245, 2022). "Based on these findings, we examined whether stimulation of the innate immune system in response to viral infection, induced MACROH2A1 as in these omics analyses." (PMID 36451245, 2022).
COVID-19 (1 paper, 2022). A disease caused by infection with severe acute respiratory syndrome coronavirus 2. "Consistent with the findings of PBMC scRNA-seq, MACROH2A1 was more highly expressed in monocytes and macrophages in the COVID-19 autopsy specimens than in controls." (PMID 36451245, 2022). "Subsequently, to investigate the involvement of MACROH2A1 in the pathogenesis of severe COVID-19, we examined its expression in immune cells by scRNA-seq of PBMC." (PMID 36451245, 2022). "Consistently, single-nucleus RNA sequencing of lung tissues revealed that MACROH2A1 was highly expressed in monocytes and macrophages and was significantly elevated in fatal COVID-19." (PMID 36451245, 2022). "We analyzed the previously generated single-nucleus RNA sequencing (snRNA-seq) data of lung tissue using autopsy specimens from 19 patients with COVID-19 and seven control specimens to further examine the involvement of MACROH2A1 in COVID-19 pneumonia." (PMID 36451245, 2022). "Our findings highlight that MACROH2A1 in extracellular vesicles is a potential biomarker of refractory COVID-19 and may reflect the pathogenesis of COVID-19 in monocytes." (PMID 36451245, 2022). "Although the mechanism of MACROH2A1 regulation of the pathogenesis of severe COVID-19 is unclear, it may function in a cell-specific manner, which makes it a potential therapeutic target with fewer side effects." (PMID 36451245, 2022). "It has also been reported that SRCs contribute to HIV reactivation via mTOR and STAT2, and MACROH2A1-SRC family axis may regulate the inflammatory pathogenesis of COVID-19." (PMID 36451245, 2022). "Although the involvement of MACROH2A1 in the pathogenesis of severe COVID-19 and its secretion into EVs remains unclear, several possibilities can be considered." (PMID 36451245, 2022). "Therefore, MACROH2A1 identified by proteomic analysis was elevated in serum EV and locally in the lungs in fatal cases; it can be considered a biomarker candidate that is closely related to the pathogenesis of refractory COVID-19." (PMID 36451245, 2022). "In our pathway analysis in scRNA-seq of monocytes in PBMCs and in previous reports, type I IFN signaling was suppressed in severe COVID-19 cases, suggesting that MACROH2A1 may be involved in the pathogenesis of refractory COVID-19 through the regulation of typeIIFN production." (PMID 36451245, 2022). "Furthermore, we propose that it may be involved in the pathogenesis of severe COVID-19 via its function in the monocyte lineage and in the innate immune response to SARS-CoV-2, and additionally, that drug discovery targeting MACROH2A1 could be considered." (PMID 36451245, 2022). "With regard to interaction with ERBB2, a key molecule in estrogen signaling involved in the upstream molecular network of MACROH2A1; ERBB2 was reported to interact with MACROH2A1.2, but not with MACROH2A1.1, which might result in MACROH2A1.2-specific function in severe COVID-19 pathogenesis." (PMID 36451245, 2022).
promyelocytic leukemia (1 paper, 2019). "We stably knocked down (KD) macroH2A1.1 mRNA in human promyelocytic leukemia HL-60 and monocytic THP-1 cell lines grown in suspension, using lentivirally transduced shRNAs against the H2AFY gene." (PMID 31439048, 2019).
tauopathies (1 paper, 2025). "Overall, RBPs enriched in disease-associated modules included the previously validated CHD4, MACROH2A1, SAFB, WDR82, and PAPOLA proteins, highlighting their potential relevance to tauopathies." (PMID 41205924, 2025).